TLCD5 (TLC domain containing 5)
Synonyms: TMEM136; MGC17839
Tractability: Antibody: UniProt predicts a signal peptide or a membrane-spanning region.
Gene: Protein-coding gene on chromosome 11 (120,325,180 to 120,333,686, forward strand). Ensembl gene ENSG00000181264.
Subcellular location: Membrane
Subcellular location (Human Protein Atlas): Vesicles; Cytosol
Gene Ontology:
Cellular component: membrane
Genetic constraint (gnomAD): Loss-of-function variants: 15 observed, 22 expected, observed/expected ratio (o/e) 0.68, 90% interval 0.46 to 1.05. The upper end of that interval is the gene's LOEUF score, 1.05, which puts it in group 4 of 6, group 1 being the genes least tolerant of losing a copy. Missense variants: 289 observed, 319.66 expected, observed/expected ratio (o/e) 0.9, 90% interval 0.82 to 1. Synonymous variants: 107 observed, 120.86 expected, observed/expected ratio (o/e) 0.89, 90% interval 0.76 to 1.04.
Homologues: Orthologues: chimpanzee TLCD5 (99% identical), macaque TLCD5 (99% identical), dog TLCD5 (96% identical), guinea pig TLCD5 (95% identical), pig TLCD5 (95% identical), mouse Tlcd5 (93% identical), rabbit TLCD5 (93% identical), rat Tlcd5 (91% identical), tropical clawed frog tlcd5 (71% identical), zebrafish tlcd5b (58% identical), zebrafish tlcd5a (56% identical).
Diseases named in the same sentence as TLCD5 in open-access papers:
TLCD5 is named in the same sentence as 4 diseases in open-access papers, as found by Europe PMC text mining. Sharing a sentence is not in itself a finding about the gene and the disease.
TLCD5 shares sentences with these, for which no sentence is quoted: colorectal cancer (1 paper); colorectal tumors (1); exfoliation glaucoma (1); primary angle-closure glaucoma (1).